FLT3 (fms related receptor tyrosine kinase 3)
Diseases named in the same sentence as FLT3 in open-access papers (continued):
Sharing a sentence is not in itself a finding about the gene and the disease.
leukemia (continued). "Moreover, NUP98 fusions co-occur with additional mutations, including FLT3-internal tandem duplication, which drives increased proliferation and further promotes leukemia development and progression." (PMID 40264981, 2025). "Radomska and colleagues recently reported that FLT3 activation by its genetic mutation inhibits C/EBPα-induced myeloid differentiation through ERK1/2-mediated phosphorylation, and that FLT3 inhibitors can promote differentiation in leukemia cells with FLT3 mutations." (PMID 38466568, 2024). "Collectively, the evidence suggests that the inhibition of autophagosome formation may potentially complement the clinical effects of molecular targeted therapy against FLT3 mutation–induced AML by promoting leukemia cell differentiation." (PMID 38466568, 2024). "Finally, to explore possible associations between genetic information and patients’ cellular abundances, we incorporate the karyotype information and the FLT3-ITD mutational status which is a well-known hotspot mutation in leukemia." (PMID 39021803, 2024). "Importantly, succinyl-CoA level and POLRMT succinylation are downregulated in FLT3-mutated clinical leukemia samples, linking enhanced mitobiogenesis to cancer progression." (PMID 38649537, 2024). "Co-occurrence of TET2 mutations with FLT3-ITD mutations may result in the development of leukemia inducing synergistic gain-of-function effects on DNA methylation, therefore gene expression." (PMID 38696033, 2024). "Activating mutations of FLT3 have a strong association with leukemias including AML." (PMID 38495876, 2024). "Studies have shown that the drug can treat leukemia and FLT3-mutated mastocytosis." (PMID 38650009, 2024). "Notably, CTS2016 effectively reduced tumor burden in a leukemia model with the drug-resistant FLT3-ITD-F691L mutation and displayed selectivity over other kinases, reducing off-target toxicities." (PMID 39367387, 2024). "Flt3 is associated with hematopoetic malignancies, and its expression evident in human leukemias." (PMID 39498386, 2024). "For AML with FLT3 mutation, small molecule tyrosine kinase inhibitors such as sorafenib, midostaurin and sunitinib have been available for the inhibition of the FLT3 signaling pathway and for the targeted killing of leukemia cells." (PMID 36824144, 2023). "Similarly, in another study, the multi-kinase inhibitor midostaurin triggered G1 arrest in FLT3-mutated leukemia cells and G2/M arrest in FLT3-WT leukemia cells, although the mechanisms involved remain unresolved." (PMID 36865133, 2023). "Therefore, we first evaluated the anti-leukemia activity of CG-806 in AML cell lines with different FLT3 mutation status." (PMID 36865133, 2023). "While certain mutations (e.g., DNMT3A, TET2, and ASXL1) are frequently observed in clonal hematopoiesis and seem to occur relatively early in leukemogenesis, others tend to emerge later during the progression of leukemia, they include mutations in FLT3, NRAS, and RUNX1." (PMID 37958832, 2023). "Circ-MYBL2 knockdown in leukemia cells harboring the FLT3-ITD mutation increased the number of cells in Sub-G1 and G0/G1 phases and decreased ones in S and G2/M phases, thus substantially impairing the proliferation of these cells, whereas it merely affected the FLT3-nonmutant cells." (PMID 37124518, 2023). "The data above showed that sorafenib-resistant leukemia cells expressed higher autophagy, suggesting autophagy activation might be associated with FLT3 inhibitor resistance in FLT3-ITD-positive AML." (PMID 35794565, 2022). "Autophagy might be stimulated by acquired mutation or BME, and then decrease the anti-leukemia effect of FLT3 inhibitors via bypass activation of FLT3 downstream signaling." (PMID 35794565, 2022).
leukemia (continued). "We next determined the effect of SNDX-5613 on in vivo leukemia-initiating potential of primary PD AML cells harboring MLL-AF9 plus FLT-3 N676T, as well as mutations in KMT2C, KMT2D, NOTCH2, IRF8, ARID1A, VPS13A, and ABCA7, which were determined by whole-exome sequencing." (PMID 35017466, 2022). "While KMT2A-PTD mutations are typically associated with poor prognosis, isolated KMT2A-PTD mutations are not sufficient to establish leukemic transformation of hematopoietic cells, highlighting the importance of cooperating genetic lesions, such as FLT3 mutations in KMT2A-rearranged leukemias." (PMID 35387132, 2022). "However, B-CLC1 demonstrated significant enrichment of FLT3, a hematopoietic trait with pathogenic effects on clinical outcome, commonly associated with leukemia-driving mutations in childhood ALL45." (PMID 35354797, 2022). "This study also showed that patients who received non-intensive salvage therapy regimens (LDAC-based or hypomethylating agents) had less proliferating FLT3-ITD-mutated AML with more frequent features common to leukemia seen in older patients (e.g., secondary AML, IDH mutations)." (PMID 35681796, 2022). "In addition, FLT3 inhibitors have been shown to cause anti-proliferative activity, in leukaemia cell lines with FLT3-ITD, through the downregulation of MCL-1 and BIRC5, the latter via the STAT3/5 pathway." (PMID 34638823, 2021). "Our findings may allow establishment of a new therapeutic option, alemtuzumab, to treat leukemia with the FLT3-ITD mutation." (PMID 34035227, 2021). "Because FLT3 mutation is insufficient to induce leukemia, additional gene aberration is necessary." (PMID 33836835, 2021). "FLT3 mutation combined with AML1-ETO gene fusion can lead to the onset of leukemia." (PMID 33836835, 2021). "As treatment response to FLT3 inhibitors may be short-lived, with leukemia relapse as the major cause of treatment failure, compounds targeting STAT5 may enhance and prolong effects of FLT3 inhibitors in this subset of patients with FLT3-mutated AML." (PMID 34360855, 2021). "Thus, we present the data showing a new potential therapeutic option, alemtuzumab, for the treatment of leukemia with the FLT3-ITD mutation." (PMID 34035227, 2021). "Furthermore, the persistence of leukemia-associated mutations, such as FLT3-ITD, NPM1, and CEBPA mutations, after the initial course of standard induction chemotherapy imparts a significantly increased risk of subsequent leukemic relapse and death." (PMID 34422653, 2021). "Therefore, combination therapies offer a strategy to contend with multiple mutations and other mechanisms of TKI resistance in mutant FLT3 leukemia." (PMID 33658483, 2021). "Furthermore, FLT3-ITD leukemias with mutations in NPM1 or DNMT3A exhibit a different drug response mechanism to the FLT3 inhibitor quizartinib, where the cell differentiation effect predominates over the cytotoxic mechanism." (PMID 33592069, 2021). "Of note is that other predictors than FLT3/ITD mutation may play a role in leukemia relapse after transplantation." (PMID 32333156, 2020). "Given the promising results in murine leukemia models with co-occurring mutations, we then evaluated the ex vivo activity of TP-0903 and TKIs in human primary samples with coexisting recurrent mutations (e.g., FLT3-ITD, IDH1/2, ASXL1, DNMT3A, NPM1, and SRSF2)." (PMID 33268594, 2020). "It is suggested that FLT3 mutation affected leukemia via these processes." (PMID 32547322, 2020). "These probes reduced cellular FLT-3 levels in leukemia MOLM-14 cells harboring FLT3 ITD mutation." (PMID 32404196, 2020). "NUP98-NSD1 leukemia frequently co-occurs with mutations in FLT3, NRAS, WT1, and MYC and is associated with poor prognosis, with patients showing a poor response to conventional therapy such as chemotherapy and allogeneic hematopoietic stem cell transplantation (allo-HCT)." (PMID 32993115, 2020).
leukemia (continued). "Importantly, serum FST levels were positively correlated with the percentage of leukemia blast in PB from FLT3/ITD‐mutated primary AML patients at diagnosis." (PMID 32134197, 2020). "However, mutational frequencies account for 25% of all FLT3-mutated leukemias and about 7% of all adult AML." (PMID 32033196, 2020). "We demonstrated here for the first time that two ULK1 inhibitors, MRT 68921 and SBI-0206965, induced caspase-dependent apoptosis preferentially in FLT3-ITD-mutated leukemia cell lines and primary leukemic blasts obtained from FLT3-ITD AML patients, while sparing normal CD34 (+) cells." (PMID 32393312, 2020). "Effective therapeutic targeting of either NPM1c or FLT3 mutations might be expected to debulk the leukaemia but with only transient benefit." (PMID 30568172, 2019). "Notably, ZEB2-BCL11B rearrangements co-occurred with FLT3 mutations and were associated with a poorly differentiated or mixed phenotype leukemia." (PMID 31817495, 2019). "Our data regarding comparative metabolomics characterized a distinct metabolic and redox adaptation that may contribute to sorafenib resistance in FLT3/ITD-mutated leukemia cells." (PMID 30947742, 2019). "Another study showed that up regulation of FLT3 gene is a potential risk factor of leukemia." (PMID 31565544, 2019). "However, FLT3 is implicated in inflammation, immunity and autoimmune diseases and is overexpressed in leukemia." (PMID 30237882, 2018). "Importantly, we recently found that BBR effectively inhibits MV4-11 cells, an FMS-like tyrosine kinase 3 (FLT3)-mutated human AML cell line that is resistant to the commonly used anti-leukemia drug cytarabine (Ara-C)." (PMID 30290822, 2018). "In most cases, this is due to activating mutations in the FLT3 gene but a significant number of leukemias are also characterized by a higher than normal expression level of un-mutated, wild-type FLT3, thus underscoring the importance of FLT3 signaling perturbations in malignant transformation." (PMID 28538663, 2017). "A combination of types 1 and 2 oncogenes would then create a perfect storm for leukaemia development, as illustrated for example by the combination of activating growth factor mutations (Flt3 or c-Kit) in combination with translocations involving the Runx1 transcription factor." (PMID 28429049, 2017). "Common leukemia-associated genes have been identified by the investigation of gene sets obtained by comparison of analysis 1 with analysis 3 [FLT3 and C-terminal binding protein 2 (CTBP2)] and analysis 2 with analysis 3 [NRAS and GATA binding protein 2 (GATA2)]." (PMID 29221109, 2017). "Mutations of the activation loop tyrosine of FLT3 (Y842) is a less frequent event in leukemia." (PMID 28271164, 2017). "In addition, we review current findings on the role of mutated FLT3 in leukemia and the development of FLT3 inhibitors for therapeutic use to treat AML." (PMID 28538663, 2017). "SPRED1 lowest levels were observed in FLT3-ITD mutated leukemia." (PMID 26909356, 2015). "The anti-leukemia activity of TOPK inhibition was also validated in primary blast cells obtained from three patients with AML with FLT3-ITD mutation who had relapsed after treatment with a potent FLT3 inhibitor (AC220 [quizartinib])." (PMID 26450903, 2015). "In addition, a similar effect has been observed in FLT3-ITD leukemia cells in association with pronounced WEE-1 inhibition and diminished CDK1 Tyr15 phosphorylation." (PMID 25914884, 2015). "This predisposition of FLT3-ITD may make these leukemia cells particularly vulnerable for anthracyline therapy, generating more FLT3-ITD mutations when exposed for this topoisomerase II inhibitor." (PMID 26237612, 2014). "It has been demonstrated that Plerixafor enhances the response of MLL-r ALL cells to FLT3 inhibition in xenografts, suggesting that this dual targeting may prove useful in this high-risk subset of pediatric leukemia patients." (PMID 25295230, 2014).
leukemia (continued). "In addition, emergence and subsequent elimination of leukaemia driving mutations (FLT3, MLL-PTD) in the bone marrow cells were precisely monitored using molecular biology methods." (PMID 24621818, 2014). "One of the mutations cooperating with PML-RARA in inducing leukemia could be represented by FLT3-ITD." (PMID 23936658, 2013). "To exclude cell line-specific off-target biology interfering with the effects of kinase-inhibition, we tested leukemia-driving RTK mutations in an isogenic cellular background: Various human (mutant) FLT3 or KIT isoforms were stably transfected in the IL3-dependent murine pro B-cell line Ba/F3." (PMID 23497317, 2013). "Interestingly, DHH-RHEBL1-positive patients showed higher expression of several genes known to be associated with leukemia occurrence and/or tumor progression, such as FLT3, BEX1, MUC4 and AFAP1L2." (PMID 24127550, 2013). "The depletion of the hematopoietic stem cell compartment induced by FLT3-ITD expression may help to explain why in murine models FLT3-ITD mutations fail to induce overt leukemia development." (PMID 23936658, 2013). "Altogether, we suggest that green tea polyphenols could serve as reagents for treatment or prevention of leukemia harboring FLT3 mutations." (PMID 23840454, 2013). "FLT3 mutations promote leukemia survival and proliferation and block cell differentiation." (PMID 23847761, 2013). "Interestingly, isolation of FLT3-mutated human CD34+CD38− leukemia stem cells indicated that all had the FLT3 mutation, and, injection of these cells into NOD/SCID mice resulted in leukemogenesis that was entirely FLT3 mutated." (PMID 24213503, 2012). "Moreover, this review describes novel FLT3-targeted therapies, as well as efficient combination therapies for FLT3-mutated leukemia cells." (PMID 21453545, 2011). "We screened and sequenced FLT3 mutations (point mutations and internal tandem duplications, ITDs) among 517 childhood leukemia patients, and assessed whether these mutations occurred before or after birth using sensitive "backtracking" methods." (PMID 20875128, 2010). "We screened a large population case series of pediatric leukemia for FLT3 mutations of both types and determined whether FLT3 ITD mutations were present at birth by examining DNA on the corresponding Guthrie cards." (PMID 20875128, 2010). "The "two hit" model of leukemogenesis related to FLT3 proposed by Gilliland and Griffin, hypothesizes that two specific types of mutations are required in leukemia: one mutation that promotes proliferation and another mutation that stops differentiation." (PMID 20875128, 2010). "It has been proposed that FLT3 mutation may be a late event in leukemia, given that FLT3 mutation status are often changed between paired diagnosis and relapse of adult and childhood patients with AML or ALL." (PMID 20875128, 2010). "To test this hypothesis, we examined genome-wide chromatin accessibility using assay for transposase-accessible chromatin with sequencing (ATAC-seq) to determine whether gilteritinib can remodel the chromatin landscape in leukemia cells of an AML case with mutations in the FLT3 TKD." (PMID 40181449, 2025). "In addition, HR and/or c-NHEJ deficiency could be induced by the treatment of leukemia/solid tumors with the tyrosine kinase inhibitors (TKi) against the cancer-driven oncogenic tyrosine kinases (e.g., FLT3(ITD), JAK2(V617F), c-KIT(N822K), IGF-1R, EGFR)." (PMID 36497275, 2022). "However, treatment response to FLT3 inhibitors may be short-lived, and leukemia relapse is the major cause of treatment failure, as resistance may frequently emerge." (PMID 34360855, 2021). "FLT3-mutated leukemic cells are able to reprogram the bone marrow compartment through exosomes, which may lead to suppression of normal hematopoiesis while promoting leukemia (stem-) cell proliferation." (PMID 33212779, 2020).
leukemia (continued). "Therefore, we speculated that FLT3-ITD mutations potentiallyupregulate CXCR4 expression on the surface of leukemia cells and enhance the chemotaxis of AML cells toward CXCL12, consistent with previously reported results." (PMID 31434952, 2019). "To investigate whether Flt3-ITD inhibition exerts antileukemic activity via modulation of the Myc network, we treated the human Flt3-ITD mutated leukemia cell line, MV4-11, with PKC412 at two different concentrations (0.1 mM and 1 mM) and analyzed the expression of Myc network genes." (PMID 30420889, 2018). "Besides that, FLT3L CAR-T may show comparative stronger cytotoxic capability on leukemia cells harboring FLT3-ITD mutation which is reflecting a very poor prognosis." (PMID 29716633, 2018). "Overall, our data might contribute to better understand how FLT3 may influence drug sensitivity and to develop new therapeutic approaches in order to improve the overall outcome of patients with high risk subtypes of leukemia." (PMID 27391351, 2016). "However, FLT3 overexpressing Ba/F3 cells engrafted into Balb/c mice did cause leukemia, which may have been secondary to murine FL expression in this model." (PMID 25295230, 2014). "Interestingly, Flt3 deficient leukemia samples also displayed some sensitivity to PKC412." (PMID 23977266, 2013). "Moreover, in specific leukemia subtypes characterized by the presence of mutations or rearrangements of genes such as FLT-3 or BCR-ABL resulting in high expression of constitutively activated oncoproteins, the association of HSP90 inhibitors and targeted drugs is highly effective in vitro." (PMID 23047954, 2012). "Clinical evidence suggests that the FLT3 mutation may occur in a sub-clone of the leukemia stem cell (LSC), including the finding that in the context of relapsed AML, there is loss of the ITD mutation 16% of the time and loss of the TKD mutation 50% of the time." (PMID 24213503, 2012). "Proteomics reveal that MA191 also degrades MAPK14 (p38α), a kinase upregulated in leukemia, in addition to FLT3." (PMID 42198431, 2026). "In vivo, this combination reduced leukemia burden and improved survival, suggesting a promising therapeutic strategy for AML with NPM1 or KMT2A‐r mutations and FLT3 mutations." (PMID 39887730, 2026). "Here, we identified IHCH9033, a novel selective class I HDACi, which exhibited an increased antitumor effect in FLT3-ITD AML through effectively eliminating leukemia burden and overcoming resistance to FLT3i." (PMID 39955584, 2025). "Using a combination of a mouse model of ETP-ALL and patient-derived xenografts, we identified leukemic cells co-expressing KIT and high levels of FLT3 (KF) that were most enriched for leukemia initiating activity, self-renewal, and chemoresistance." (PMID 39849166, 2025). "Quizartinib combined with SREBP inhibitor fatostatin or FASN inhibitor orlistat provided substantial therapeutic benefit over monotherapies in the murine FLT3/ITD leukemia model." (PMID 40263296, 2025). "The role of SREBP and its regulation in leukemia, particularly, over the course of oncogenic transformation by FLT3/ITD is less well understood." (PMID 40263296, 2025). "In this review, we discuss the therapeutic effects and limitations of single-agent use of currently approved targeted drugs for leukemia treatment, such as tyrosine kinase inhibitors (TKIs) and FLT3 inhibitors." (PMID 40722724, 2025). "One area of interest includes the design of dual-targeted inhibitors that, in addition to blocking FLT3, inhibit other oncogenic kinases involved in the progression of leukemia." (PMID 40547482, 2025). "FLT3/ITD–driven leukemia has also been shown to be dependent upon serine for proliferation and survival." (PMID 40263296, 2025).